ULK1 (unc-51 like autophagy activating kinase 1)
Diseases named in the same sentence as ULK1 in open-access papers (continued):
Sharing a sentence is not in itself a finding about the gene and the disease.
hepatocellular carcinoma (24 papers, 2018 to 2026). A malignant tumor that arises from hepatocytes. "LicoA activated the ULK1/Atg13 complex to induce autophagy and apoptosis via the generation of ROS in human hepatocellular carcinoma cells." (PMID 40002335, 2025). "PLIN2 inhibits the adenosine 5′-AMPK/ULK1 (human) recombinant protein-lysosome pathway and promotes cell proliferation in hepatocellular carcinoma (HCC)." (PMID 39588271, 2024). "Previous reports have shown that METTL1 promotes esophageal squamous cell carcinoma through the RPTOR/ULK1/autophagy axis and mediates m7G tRNA modification to promote lenvatinib resistance in hepatocellular carcinoma." (PMID 38822363, 2024). "Related studies have also shown that the downregulation of miR-26a/b in hepatoma cells enhances ULK1 expression, promoting autophagy and chemotherapy resistance." (PMID 38169376, 2024). "Glucose starvation also suppressed Torin1-induced activation of ULK1 in various cell types, including adipocytes, myoblasts, hepatoma cells, and mouse primary hepatocytes." (PMID 37225695, 2023). "Lowering UHMK1 expression restrained activation of ERK, which together with the ULK1-induced autophagy, inhibited cell proliferation and migration in hepatoma cells." (PMID 32580279, 2020). "The mRNA and protein levels of UHMK1 and ULK1 were then examined for validation by using samples from COX5B downregulated or overexpressed hepatoma cells." (PMID 32580279, 2020). "The results demonstrated that HDIs upregulated FOXO1 and ULK1 in hepatoma cells in a time-dependent manner, indicating their key regulatory role in HDI-induced autophagy." (PMID 32929346, 2020). "In addition, miR-26a/b is a potential autophagy inhibitor in hepatocellular carcinoma (HCC) to inhibit the expression of serine/threonine protein kinase ULK1 promoting cell apoptosis." (PMID 31405037, 2019). "In contrast, an increased ULK1 expression observed in esophageal squamous cell carcinoma, hepatocellular carcinomas, nasopharyngeal carcinoma, and the latest in human gastric cancer is a further indication of the dual role of autophagy as both a tumor suppressor and tumor promoter in cancer." (PMID 29643976, 2018). "Some research also indicates that the overexpressed PTENP1 in hepatocellular carcinoma (HCC) competitively binds with miR-17, miR-19b, and miR-20a to promote the ULK1, ARG7, and p62 autophagic genes to complete the autophagy process and to suppress HCC progression." (PMID 35097120, 2022). "Consistently, in other hepatoma cell lines, knockdown of ENDOG increased phosphorylation of mTOR and ULK1, as well as suppressed autophagy under starvation." (PMID 33473107, 2021). "Using RNA sequencing analysis, we found that FOXO1 and ULK1, two autophagy-related genes, were significantly upregulated in HDI-treated HCC cells, whereas the knockdown of FOXO1 or ULK1 blocked HDI-induced autophagy and EMT in hepatoma cells." (PMID 32929346, 2020). "In this review, we provide a comprehensive update of ULK1 mediated hepatic action involving lipotoxicity, acute liver injury, cholesterol synthesis, and hepatocellular carcinoma, including both its autophagic and non-autophagic functions." (PMID 35252196, 2022). "The present study found that HDIs could induce autophagy in hepatoma cells by upregulating FOXO1 and ULK1." (PMID 32929346, 2020). "Systemic KO of Ulk1 prevented liver cancer and reduced hepatic tumor growth in a diethylnitrosamine (DEN)-induced hepatocellular carcinoma (HCC) model, suggesting that ULK1 may be a target for treating liver cancer." (PMID 38067169, 2023). "Our results also showed that FOXO1 activation by HDIs upregulated ULK1 expression in hepatoma cells, whereas HDI treatment failed to induce ULK1 expression after FOXO1 knockdown or inhibition." (PMID 32929346, 2020).
Obesity (24 papers, 2013 to 2026). Accumulation of substantial excess body fat. "Unc-51-like autophagy-activating kinase 1 (ULK1), a key player in the initiation complex, has been implicated in obesity pathogenesis." (PMID 41439967, 2025). "In previous studies, MSCs have been shown to alleviate the muscle atrophy caused by diabetes and obesity through sEV-mediated enhancement of AMPK/ULK1-driven autophagy, thereby extending the therapeutic duration of stem cells." (PMID 38622732, 2024). "Our data suggest that obesity is associated with considerable upregulation of autophagy-promoting genes in sperm, such as Beclin1 and ULK1." (PMID 37226085, 2023). "Recent studies showed that Ulk1/Rab9-mediated mitophagy protected the heart against ischemic damage and obesity-associated cardiomyopathy in mice." (PMID 36312227, 2022). "The m6A sites on the transcripts were further determined to be the direct substrates of FTO (fat mass and obesity-associated protein), which removes the m6A mRNA modification of ULK1 transcripts, thus promoting autophagy and prolonging the half-life of ULK1 transcripts." (PMID 37581026, 2023). "Interestingly, our study showed an increase in ULK1 expression in the placentas of OB groups, possibly due to the metabolic stress caused by obesity and activating macroautophagy." (PMID 33920886, 2021). "In contrast, ULK1 Ser757 phosphorylation, a modification driven by mTOR that inhibits ULK1 activity, was elevated in aging with obesity but suppressed by DPR." (PMID 41549510, 2026). "In obesity and overnutrition, mTOR phosphorylates ULK1 protein at Ser637 and Ser757 and Atg13 at Ser258 in the ULK1 complex, inhibiting autophagosome formation." (PMID 40141412, 2025). "In conclusion, our results suggest that by secreting exosomes, hucMSCs activate AMPK/ULK1‐mediated autophagy, which ameliorates muscle atrophy in diabetes and obesity." (PMID 36708027, 2023). "Here, for the first time, we examined the association between obesity, relative sperm telomere length (STL) and autophagy-related mRNA levels such as Beclin1, AMPKa1, ULK1, BAX, and BCL2." (PMID 37226085, 2023). "More interestingly, it was found that ULK1 upregulation prevents obesity-induced cardiac dysfunction through regulating lipid metabolism." (PMID 35330106, 2022). "Obesity decreases ULK1 and leads to lipotoxicity in cardiomyocytes and consequently heart dysfunction." (PMID 32907629, 2020). "However, in obesity and insulin-resistant states, mitophagy becomes dysregulated, partly due to nutrient overload and chronic mTORC1 activation, which inhibit the ULK1 complex responsible for autophagy initiation." (PMID 40806527, 2025). "On the contrary, the knockdown of ULK1 reverses the benefits of overexpression of NR1D1 on obesity." (PMID 38348222, 2024). "Our results suggest that human umbilical cord mesenchymal stromal cells mitigate diabetes‐ and obesity‐induced muscle atrophy via enhancing AMPK/ULK1‐mediated autophagy through exosomes, with implications of applying hucMSCs or hucMSC‐derived exosomes to treat muscle atrophy." (PMID 36708027, 2023). "With this in mind, our purpose was to examine the association between obesity, relative STL, mRNA expression of autophagy-related genes (Beclin1, AMPKa1, ULK1, BAX, and BCL2), values of semen parameters, sperm DNA integrity, chromatin maturation, apoptotic changes, and intracellular ROS levels." (PMID 37226085, 2023). "A recent study has uncovered the protective role of ULK1 in obesity-induced cardiac damage." (PMID 32907629, 2020). "Therefore, monitoring the miRNAs that regulate the ULK1 complex during obesity would have positive effects on the vascular bed." (PMID 32907629, 2020). "Suggestive evidence implicated the UNC‐51‐like kinase (ULK1) gene, and it was observed that four rare variants that were more common in the Swedish SCZ cases were also more common in UK10K SCZ cases, as compared to obesity cases." (PMID 29148569, 2018).
Obesity (continued). "ULK1 expression in different cells isolated from the heart tissues (cardiomyocytes, fibroblasts, smooth muscle cells, and endothelial cells) of a mouse model of obesity showed a substantial reduction in the phosphorylation and its protein level just in cardiomyocytes compared to non-obese mice." (PMID 36841820, 2023). "In agreement with the activation of AMPK, other AMPK substrates, UNC-51-like kinase 1 (ULK1), and Mitochondrial fission factor (MFF) are increased in the liver of L-Ago2 KO mice, suggesting enhanced autophagy/mitophagy and improved mitochondrial quality in the Ago2-deficient liver in obesity." (PMID 30201950, 2018). "Here, for the first time, we evaluated changes in autophagy-related genes (AMPKa1, Beclin1, ULK1, BAX, and BCL2) mRNA expression in spermatozoa from patients with obesity." (PMID 37226085, 2023). "Regarding mRNA expression, there was considerable upregulation of Beclin1, ULK1, and BCL2 in the group with obesity compared to the normal-weight group." (PMID 37226085, 2023). "Considering mRNA expression, Beclin1 (p = 0.0002), ULK1 (p < 0.0001), and BCL2 (p = 0.0101) were significantly upregulated in the group with obesity compared to the normal-weight group." (PMID 37226085, 2023). "We reported significant up-regulation in mRNA expression of Beclin1, ULK1, and BCL2 in the patients with obesity." (PMID 37226085, 2023). "In this study, we demonstrate that dietary DPR attenuates cardiac inflammaging, characterized by chronic, low‐grade inflammation in aged hearts with obesity, through the activation of the AMPK‐UNC51‐like kinase 1 (ULK1) signaling axis, thereby promoting mitochondrial quality control." (PMID 41549510, 2026). "Previous research has reported that Cel ameliorates mitochondrial function in obesity models via the AMPK/SIRT1 axis, and this work for the first time reveals a novel mechanism by which it regulates autophagy through the AMPK/ULK1 pathway in the context of AS." (PMID 41347171, 2025). "Despite the preventive role of ULK1 in the context of obesity-induced damage, the relation between ULK1 and endothelial dysfunction in obesity has not been studied." (PMID 32907629, 2020).
pancreatic cancer (24 papers, 2016 to 2025). "In this part, we figured out that PPARγ might regulate mTOR-mediated degradation of ULK1, linked to impaired mitophagy in pancreatic cancer cells." (PMID 35186942, 2021). "First, we showed that ULK1 associates with NEDD4L in pancreatic cancer cells." (PMID 31959741, 2020). "This staining pattern was also observed in TMA of grade 1 and 2, consistent with high ULK1 activity observed in human pancreatic cancers." (PMID 41408407, 2025). "Rapamycin-induced GFP-LC3 puncta formation was also significantly impaired in ULK1 KO human pancreatic cancer cells, further confirming autophagy suppression and defect in viability." (PMID 41408407, 2025). "To further dissect how ULK1 shapes the immune landscape in pancreatic tumors, we profiled cytokine and chemokine expression in pancreatic tissues from KPC control (KPC;Ulk1fl/+) and KPC Ulk1 KO (KPC;Ulk1fl/fl) mice." (PMID 41408407, 2025). "Here, we suggest ULK1 as a critical regulator of pancreatic tumor progression through both cell-intrinsic and immune-modulatory mechanisms." (PMID 41408407, 2025). "Genetic deletion of Ulk1 impaired autophagy and reduced cell proliferation, colony formation and invasiveness of pancreatic cancer cells." (PMID 41408407, 2025). "To investigate the functional role of ULK1 in pancreatic cancer progression, we generated Ulk1 KO KPC cells using CRISPR–Cas9, which was confirmed by genomic sequencing and quantitative PCR with reverse transcription." (PMID 41408407, 2025). "Our findings also indicated that TET promoted the upregulation of ULK1 protein expression in pancreatic cancer cells." (PMID 38987818, 2024). "Overexpressed NEDD4L was found to repress autophagy in pancreatic cancer cells by decreasing cellular levels of the autophagy protein ULK1 and the glutamine transporter ASCT2." (PMID 36918822, 2023). "The inhibition of ERK phosphorylation could suppress cancer-stromal interactions in pancreatic cancer and promote the ULK1 degradation process, leading to an improved invasive phenotype under hypoxia and osteolytic bone metastasis in BC cells induced by ULK1 deficiency." (PMID 37751436, 2023). "As such, inhibition of ULK1 phosphorylation at S405 and S415 in pancreatic cancer cell lines significantly decreased their survival rates under starvation conditions." (PMID 33654220, 2021). "In the current study, we observed activation of ULK1-mediated autophagy as a mechanism of apoptotic effects of PVT in pancreatic cancer." (PMID 34830816, 2021). "Analysis of Cancer genomic R2 and GEPIA databases revealed that ULK1 was differentially expressed in human pancreatic tumors when compared to that of normal tissues." (PMID 34830816, 2021). "Inhibition of ULK1 phosphorylation at these two residues led to decreased pancreatic tumor cell survival, underpinning the reliance of the tumor cells on autophagy." (PMID 34356465, 2021). "Further, we found that regulation of ULK1 by ubiquitination in multiple cancer cell lines and an in vivo model of pancreatic cancer altered cancer proliferation and survival." (PMID 34502089, 2021). "Pancreatic cancer patients exhibit reduced levels of autophagy initiator gene, ULK1, which correlated with reduced patient survival." (PMID 34830816, 2021). "Clinical significance of ULK1 in normal and pancreatic cancer patients was evaluated by R2 and GEPIA cancer genomic databases." (PMID 34830816, 2021). "To further explore the physiological implications of ULK1 phosphorylation at S405 and S415, we examined the phosphorylation levels of ULK1 in several pancreatic cancer cell lines." (PMID 33654220, 2021). "Treatment with BIO substantially reduced ULK1 S405 and S415 phosphorylation and rendered pancreatic cancer cells more vulnerable to starvation stress than HPNE cells." (PMID 33654220, 2021). "The 5-year survival rate was approximately 40% in pancreatic cancer patients with high ULK1 expression as compared to <20% in low ULK1 expressing pancreatic cancer patients." (PMID 34830816, 2021).
pancreatic cancer (continued). "This phosphorylation status of ULK1 is well correlated with the high expression levels of GSK3B in pancreatic cancer cell lines, compared with HPNE cells." (PMID 33654220, 2021). "Further, they found high levels of this type of ULK1 modification in human pancreatic cancer cell lines that exhibited increased autophagy, suggesting possible implications for the development of certain cancerous tumors." (PMID 33654220, 2021). "R2 software analysis demonstrated that pancreatic cancer patients exhibited 56% reduced expression of ULK1, when compared with normal patients." (PMID 34830816, 2021). "Oral administration of PVT significantly suppressed the growth of pancreatic tumor xenografts by inducing ULK1-mediated autophagy." (PMID 34830816, 2021). "Increased phosphorylation of ULK1 at S405 and S415, which lead to its activation, is found in several human pancreatic cancer cell lines." (PMID 34356465, 2021). "NEDD4L and ULK1 levels were inversely correlated in two different pancreatic cancer mouse models-xenograft mouse and KPC mouse models." (PMID 31959741, 2020). "Mechanistic studies have demonstrated that ZKSCAN3 inhibits pancreatic cancer cell proliferation, migration, and invasion by transcriptionally activating the expression of autophagy core genes, such as ULK1 and LC3-II, and promoting autophagosome formation and lysosomal degradation functions." (PMID 40723888, 2025). "The study concludes that targeting ULK1 could be a promising strategy for treating pancreatic cancer by both inhibiting autophagy and enhancing the body’s immune response against tumors." (PMID 41408407, 2025). "Similarly, increases in ULK1 and pATG14 levels were observed in human pancreatic cancer cell lines compared with normal human pancreatic epithelial and fibroblast (IMR90) cells." (PMID 41408407, 2025). "Histological analysis showed only crucial abnormalities in pancreas rather than other tissues, although occasional lung pathology was observed in positive control (KPC;Ulk1fl/+) mice, suggesting that Ulk1 deletion specifically impacts pancreatic tumor development." (PMID 41408407, 2025). "Targeting ULK1 may represent a promising therapeutic strategy by inhibiting autophagy and enhancing antitumor immune responses in pancreatic cancer." (PMID 41408407, 2025). "Importantly, our in vivo studies using both syngeneic orthotopic allografts and spontaneous KPC GEM models provide compelling evidence that Ulk1 is required for pancreatic tumor development in a physiological setting." (PMID 41408407, 2025). "This study explores the role of a protein called ULK1 in pancreatic cancer." (PMID 41408407, 2025). "ULK1 has been shown to be involved in the generation of its autophagy in many diseases, for example, in pancreatic cancer, NEDD4L can interact with ULK1 to reduce ULK1 expression to inhibit autophagy and mitochondrial metabolism, which in turn inhibits the survival of pancreatic cancer cells." (PMID 38887520, 2024). "NEDD4L binds to ULK1 in pancreatic cancer cells and is involved in the ubiquitination and subsequent degradation of ULK1 to downregulate autophagy and mitochondrial metabolism, ultimately suppressing the growth and survival of pancreatic cancer cells." (PMID 38027016, 2023). "An E3 ubiquitin ligase, NEDD4L, inhibits ULK1 in pancreatic cancer cells by deregulating its protein stability and reduces tumor cell growth by exhibiting the opposite effects between ULK1 expression in the KPC mouse model and the xenograft mouse model of shNEDD4L cells." (PMID 38067169, 2023). "Similarly, GEPIA database suggests that ULK1 was significantly downregulated in human pancreatic tumor tissues compared to that of normal tissues." (PMID 34830816, 2021). "Furthermore, a marked increase in the phosphorylation of ULK1 on these residues was observed in human pancreatic cancer cell lines, suggesting the potential importance of this novel ULK1 phosphorylation for tumorigenesis in the pancreas." (PMID 33654220, 2021).